HIF1A (hypoxia inducible factor 1 subunit alpha)
Diseases named in the same sentence as HIF1A in open-access papers (continued):
Sharing a sentence is not in itself a finding about the gene and the disease.
gastric cancer (358 papers, 2006 to 2026). A primary or metastatic malignant neoplasm involving the stomach. "In tumor-associated macrophages of gastric cancer, HIF-1α suppresses the expression of miR-30c and results in increased REDD1 expression." (PMID 41462930, 2025). "The target proteins implicated in gastric cancer, specifically HIF1A, HSP90AA1, MMP9, ERBB2, and PTGS2, were matched with the key metabolites from the Vaccinium genus, including cyanidin 3-O-glucoside, ursolic acid, resveratrol, scopoletin, and (+)-catechin." (PMID 40141751, 2025). "Another experiment indicated that iron death is associated with chemoresistance in gastric cancer, where HIF-1α promotes its accumulation by regulating the expression of lncRNA-PMAN, thus forming the HIF-1α/PMAN/ELAVL1 regulatory axis." (PMID 40861273, 2025). "Hypoxia, a hallmark feature of the gastric cancer microenvironment, coordinates three tumor-promoting processes—tumor cell adaptation, immune suppression, and metastasis—through the HIF-1α-Adora2b axis." (PMID 41346607, 2025). "This interplay between ERBB3 and SLC1A1 appears to involve HIF1α, which can be upregulated by heregulin and has been implicated in ferroptosis resistance in gastric cancer." (PMID 40846695, 2025). "A direct transcriptional upregulation of CPT1C by the hypoxia-inducible factor HIF1α was similarly found in gastric cancer and was associated with the malignant proliferative behavior of gastric cancer cells." (PMID 39596847, 2024). "We next assessed the ability of H. pylori clinical strains isolated from patients from low versus high gastric cancer risk regions in Colombia to induce HIF-1α." (PMID 37828903, 2023). "Hypoxia and increased HIF-1α are associated with increased expression of stem cell markers in gastric cancer cell models and patient samples." (PMID 36846589, 2023). "In summary, our findings indicate that IDF-11774, an inhibitor of HIF-1α, causes a significant reduction in the proliferation, migration, and invasion capabilities of gastric cancer cells." (PMID 38140111, 2023). "Our findings demonstrated that P4HB plays a significant role in the regulatory network of HIF-1α and is closely linked with invasion and metastasis in gastric cancer cells under hypoxic conditions." (PMID 31467922, 2019). "VEGF expression is upregulated in EBV-associated gastric cancer and influenced by the overexpression of hypoxia-inducible factor-1 alpha (HIF-1α)." (PMID 29865171, 2018). "Diagnostic and prognostic values of HIF-1α for gastric cancer were analyzed, and the interactions between HIF-1α, VEGF, and PI3K/AKT pathways were explored." (PMID 29899167, 2018). "All these data indicate that serum HIF-1α is a sensitive and reliable prognostic and diagnostic marker for gastric cancer." (PMID 29899167, 2018). "More importantly, scavenging of ROS by the antioxidant N-acetylcysteine (NAC) attenuated activation of NF-κB and HIF-1α in autophagy-deficient gastric cancer cells, and autophagy inhibition induced metastasis and glycolysis were also diminished by NAC in vivo." (PMID 26497999, 2015). "In this study, we aimed to establish a therapeutic model demonstrating that hypoxia-induced apoptosis via the overproduction of ROS can be introduced to HIF-1α deficient gastric cancer cells." (PMID 26339797, 2015). "HIF-1α expression can be used to stratify patients at higher risk for poor prognosis, and is potentially an important therapeutic target in gastric cancer patients." (PMID 24614305, 2014). "Previous studies showed up-regulation of HIF-1α expression in gastric cancer tissues and cells, whereas the precisely underlying regulatory mechanisms remain to be defined." (PMID 24927122, 2014). "HIF-1α overexpression is associated with increased mortality in patients with various tumors, including gastric cancers." (PMID 24216696, 2013).
gastric cancer (continued). "HIF-1α deficient gastric cancer cells display significantly increased anoikis susceptibility due to an upregulated α5 integrin expression, suggesting a pivotal role for HIF-1α in anoikis control via suppression of α5 integrin." (PMID 24216696, 2013). "In conclusion, the present study demonstrates for the first time that the loss of HIF-1α contributes to the development of aggressive peritoneal dissemination by upregulating MMP-1 in gastric cancer cell lines." (PMID 23181099, 2012). "HIF-1α is expressed in most gastric cancers, and HIF-1α expression at the invading tumor edge is associated with advanced-stage disease, lymph node metastases, and poor survival." (PMID 21584218, 2010). "By applying a lentivirus-based siRNA system we show significantly enhanced 5-FU and cisplatin toxicity in HIF-1α-deficient gastric cancer cells." (PMID 20706634, 2010). "The prognostic impact of HIF-1α expression in gastric cancer appears to be dependent on the staining pattern with HIF-1α expression at the invasive tumour edge associated with a poor prognosis and focally positive expression a better prognosis." (PMID 17179985, 2007). "In the present study, we showed that HIF-1α overexpression and loss of p21expression in gastric cancers correlated with poor patient prognosis, compared to tumors that retained p21 expression, or had lost HIF-1α expression." (PMID 17166265, 2006). "HIF1A is consistently linked to primary tumors and early gastric cancer, where high expression correlates with tumor progression, poorly differentiated cell types, and elevated VEGF expression, which all contribute to tumor growth, angiogenesis, and metastasis." (PMID 40141751, 2025). "NF-κB activation was limited in HIF-1α deficient gastric cancer cells upon treatment with 5-FU." (PMID 37086261, 2023). "Therefore, the question to be asked is what is the association of gastric cancer metastasis with HIF-1α and NDRG2?" (PMID 33817155, 2019). "Serum HIF-1α showed promising diagnostic and prognostic values for gastric cancer." (PMID 29899167, 2018). "We noted that gastric cancer cells are able to functionally compensate the stable loss of HIF-1α." (PMID 26760764, 2016). "By us, the NF-kB pathway is strongly repressed in gastric cancer cells upon stable loss of HIF-1α." (PMID 26760764, 2016). "Hypoxia-inducible factor (HIF)-1α is an important transcription factor that regulates oxygen homeostasis, and may be associated with the occurrence of gastric cancer." (PMID 25997455, 2015). "Gastric cancer metastasis-associated genes, including hypoxia-inducible factor (HIF)-1α, matrix metalloproteinase (MMP)-2, MMP-9, basic fibroblast growth factor (bFGF), and urease plasminogen activator (uPA) were measured by RT-sqPCR prior to and following transfection with the KAI1 gene." (PMID 26622792, 2015). "When stratifying the distant metastasis of gastric cancer, HIF-1α expression was significantly associated with distant metastasis in 5 studies (469 patients; OR = 6.635, 95% CI = 1.855–23.738, P = 0.004), although, with evident between-study heterogeneity (I2 = 73.3%, subgroup difference P = 0.005)." (PMID 24647137, 2014). "HIF-1α overexpression has been linked to poor gastric cancer prognosis." (PMID 24614305, 2014). "To study whether DEC1 is associated with HIF-1α in gastric cancer, we performed a correlative analysis." (PMID 23445622, 2013). "Finally, an immunohistochemical analysis using 95 resected cancer tissues revealed that the HIF-1α expression is an independent risk factor for relapse in gastric cancer patients who postoperatively undergo 5-FU chemotherapy." (PMID 24216696, 2013). "Loss of HIF-1α may contribute to the development of aggressive peritoneal dissemination via the upregulation of MMP-1 in gastric cancer cells." (PMID 23181099, 2012).
gastric cancer (continued). "To evaluate the importance of HIF-1α for the sensitivity of human gastric cancer cells towards established chemotherapeutic agents, we compared the effects of 5-FU and cisplatin in HIF-1α-competent (scrambled, “SCR”) and HIF-1α-deficient (knockdown, “KD”) AGS cells." (PMID 20706634, 2010). "Therefore, we have conducted a comprehensive analysis of the role of HIF-1α for pivotal metastasis-associated processes of human gastric cancer." (PMID 19223895, 2009). "Similarly the HIF-1α regulated CA9 was expressed at the invasive tumour edge in a subset of gastric cancer where it was associated with tumour invasion, advanced disease and a poor prognosis." (PMID 17179985, 2007). "Furthermore, we found that nuclear expression of HIF-1α was closely associated with poor prognosis in gastric cancer patients (P < 0.001) and could serve as an independent risk factor." (PMID 41710663, 2026). "Although we previously reported that elevated HIF‐1α expression is associated with an aggressive phenotype in gastric cancer (GC), little is known about the antitumor effects of FTIs on GC." (PMID 33773069, 2021). "Besides the up-regulation of HIF-1α expression, we also found that autophagy defect could cause an increase in cytoplasmic and mitochondrial ROS levels in gastric cancer cells, which is consistent with previous studies." (PMID 26497999, 2015). "The results show that B7H3 and HIF-1α mRNA are significantly upregulated in gastric cancer, with a strong positive correlation between their expressions." (PMID 41710663, 2026). "In this study, we explored the expression characteristics and correlation of B7H3 and HIF-1α in large gastric cancer samples using bioinformatics and immunohistochemical methods." (PMID 41710663, 2026). "Our findings demonstrated that Zn-Quer NZs effectively reducedNOX4 expression and ROS production in gastric cancer cells while alsodownregulating HIF-1α to decrease vascular endothelial growthfactor expression." (PMID 41505409, 2026). "Recent studies have highlighted the roles of key enzymes (e.g., HK2 and PKM2) and signaling pathways (e.g., PI3K/Akt/mTOR, c-Myc, HIF-1α) in gastric cancer metabolism." (PMID 41220952, 2025). "The expression of CLDN6 is reduced in gastric cancer associated with pathological stage; however, ATAD2 expression is high due to Hypoxia‐inducible factor 1‐alpha (HIF1α)." (PMID 40979569, 2025). "For example, HIF-1α-mediated upregulation of P-gp and MDR1 was found to be associated with the resistance of gastric cancer cells to doxorubicin and vincristine." (PMID 40710312, 2025). "The RNA sequencing data highlight several key proteins—HIF1A, HSP90AA1, PTGS2, MMP9, and ERBB2—which are associated with various stages of gastric cancer progression and align with established biomarkers and pathways." (PMID 40141751, 2025). "Previous study indicated overactivation of the RAS/MAPK and PI3K/AKT/mTOR pathways results in the upregulation of HIF-1α, which is involved in the gastric cancer cell proliferation and invasion under hypoxic conditions." (PMID 40129974, 2025). "Elevated expression of IGF2BP2 promotes the stabilization and translation of HIF1α mRNA in an m6A-dependent manner, thereby enhancing glucose metabolism and radiotherapy resistance in gastric cancer." (PMID 40469197, 2025). "Knockdown of IGF2BP3 inhibits hypoxia-induced cell migration and angiogenesis by modulating HIF-1α in stomach cancer." (PMID 40102715, 2025). "Targeting OPN can block the PI3K/Akt/HIF-1α signaling pathway and is a potentially valuable approach for targeted therapy of gastric cancer." (PMID 40563539, 2025). "Gastric cancer cells: HIF-1α-induced Adora2b upregulation synergizes with Adora2b-mediated HIF-1α stabilization to upregulate VEGF and MMP-9, enhancing angiogenesis and invasion." (PMID 41346607, 2025).
gastric cancer (continued). "The researchers also found an increase in mRNA expression of the immunosuppressive cytokine TGF-β1 under hypoxic conditions and increased expression of HIF-1α in gastric cancer cell lines." (PMID 40216744, 2025). "It suppresses the expression of HIF-1α and other glycolytic enzymes, thus reducing glycolysis in gastric cancer cells." (PMID 41220952, 2025). "Hypoxia plays a crucial role in gastric cancer progression by inducing the expression of different lncRNAs via HIF1-α-mediated transcriptional activation." (PMID 39940704, 2025). "Gastric cancer (GC) cells display a striking reliance on glycolysis, driven by constitutive activation of the PI3K/AKT/mTOR signaling pathway and stabilization of HIF-1α—effects often amplified by Helicobacter pylori-associated chronic inflammation." (PMID 40977684, 2025). "Our study supports these findings by demonstrating that regulation of HIF1α expression and lactate production in gastric cancer by the methylated reading protein IGF2BP2 exerts a radiosensitizing effect." (PMID 40469197, 2025). "Increased expression of HIF-1α has been widely demonstrated a correlation with poor prognosis in gastric cancer patients." (PMID 40129974, 2025). "In summary, hypoxia-induced metabolic reprogramming in gastric cancer is primarily orchestrated through the HIF-1α axis." (PMID 41220952, 2025). "Reader IGF2BP3 is highly expressed in stomach cancer tissues and hypoxia-treated stomach cancer cells alongside HIF-1α." (PMID 40102715, 2025). "Linet al. reported that hypoxia-induced HIF-1α/lncRNA-PMAN inhibits ferroptosis by promoting the cytoplasmic translocation of ELAVL1 during peritoneal dissemination from gastric cancer." (PMID 40091620, 2025). "In early gastric cancer (Stages I-II), HIF-1α is expressed only minimally in the central tumor nests (occupying <15% of tumor cells), with a co-expression rate of 32% with Adora2b, failing to form a stable positive feedback loop." (PMID 41346607, 2025). "LHPP, a histidine phosphatase, inhibits glycolysis and proliferation in gastric cancer cells by suppressing glycogen synthase kinase 3 beta (GSK3b) phosphorylation and mediating hypoxia‐inducible factor 1 alpha (HIF1A)." (PMID 39802639, 2025). "Treating gastric cancer cells with DS or silencing HIF-1α can significantly inhibit the volume and number of metastatic tumors in a mouse model of gastric cancer and suppress TGF-β-mediated EMT." (PMID 40563539, 2025). "In a study of HIF-1α and the Treg surface marker Foxp3 in gastric cancer, expression of HIF-1α and Foxp3 was found to be positively correlated with tumor stage and degree of peripheral lymph node metastasis." (PMID 40216744, 2025). "Under hypoxia, HIF-1α-induced NAT10 stabilizes SEPT9 mRNA via ac4C modification, forming a NAT10/SEPT9/HIF-1α feedback loop that drives glycolysis addiction in gastric cancer." (PMID 40999468, 2025). "Apigetrin exerted its cytotoxic effects in gastric cancer cells by initiating autophagy-driven cell death through the inhibition of HIF-1α and EZH2 in both hypoxic and normoxic environments." (PMID 41155376, 2025). "This coordinated response defines HIF-1α-driven CD73 induction as a pivotal mechanism underlying hypoxic adaptation and therapeutic resistance in gastric cancer." (PMID 41441084, 2025). "Weida Wang reported that SHMT2 levels are increased in gastric cancer tissues and increase the stability of hypoxia-inducible factor 1α (HIF1α)." (PMID 39309860, 2024). "In summary, these data suggest that M2‐EX‐derived MALAT1 upregulates HIF‐1α by sponging miR‐217‐5p in gastric cancer cells." (PMID 38639382, 2024). "In conclusion, we identified that M2 TAMs secreted exosomes to transmit MALAT1 to gastric cancer cells, in which MALAT1 stabilized the δ‐catenin protein and upregulated HIF‐1α expression, leading to enhanced glycolysis and gastric cancer progression." (PMID 38639382, 2024).
gastric cancer (continued). "Hypoxia induces miR-224 expression, which is associated with HIF-1α and Ras-associated domain-containing protein 8 (RASSF8) in samples of gastric cancer tissue and gastric cancer SGC-7901 and MGC-803 cells." (PMID 38766303, 2024). "The activation of β‐catenin and HIF‐1α signaling pathways by M2 TAM exosomes collectively led to enhanced aerobic glycolysis in gastric cancer cells." (PMID 38639382, 2024). "In gastric cancer, c-Myc collaborates with HIF-1α, a key protein in activating AEG, to enhance the expression of glycolytic enzymes like Glucose Transporters (GLUT), HK2, PFK, PGK, and LDHA, significantly elevating AEG levels in tumor cells." (PMID 39906672, 2024). "Taken together, these results indicate that M2‐EX activates β‐catenin and HIF‐1α signaling pathways to induce aerobic glycolysis and gastric cancer progression." (PMID 38639382, 2024). "HIF-1α is crucial in all cancer hallmarks, particularly in hypoxia-induced angiogenesis and resistance to apoptosis in gastric cancer." (PMID 39816318, 2024). "In gastric cancer, miR-224-5p is induced by hypoxia and HIF-1a which inhibits RASSF8 to promote cell growth, migration, and invasion." (PMID 39714200, 2024). "CD204+ M2-like TAMs can utilize the TNF-α/NF-κB/HIF-1α/miR-210/NTN4 pathway to facilitate gastric cancer progression." (PMID 38175202, 2024). "We further confirmed that miR‐217‐5p overexpression increased while miR‐217‐5p inhibition decreased the expression of HIF‐1α in gastric cancer cells." (PMID 38639382, 2024). "Another research indicated that HIF1α-activated miR-17-5p promotes tumor growth and metastasis of gastric cancer by repressing PDCD4." (PMID 38485986, 2024). "To elucidate the correlation of HIF1A with clinicopathologic characteristics in patients with gastric cancer (GC), we conducted a systematic review and meta-analysis." (PMID 38877062, 2024). "M2 TAMs performed these effects via the release of exosomes that contained a high level of lncRNA MALAT1, which stabilized the δ‐catenin protein through lncRNA‐protein interaction and upregulated HIF‐1α via the ceRNA network in gastric cancer cells." (PMID 38639382, 2024). "It is known that hypoxia-inducible factor-1α (HIF-1α) directly binds to the Rnd3 gene promoter and drives its expression in gastric cancer cells." (PMID 38343633, 2024). "Albumin (ALB), B-cell lymphoma 2 (BCL-2), nuclear factor kappa B subunit 1 (NFKB1), hypoxia-inducible factor 1 alpha (HIF1A), and interleukin 6 (IL-6) had a higher expression in gastric cancer than in normal conditions." (PMID 39816318, 2024). "Based on the pivotal role of HIF-1α in stemness and chemoresistance in gastric cancer, the interest in identifying critical molecular targets and strategies for surpassing the action of HIF-1α is expanding." (PMID 36846589, 2023). "Here, we aimed to evaluate the anti-tumor effect of IDF-11774, a HIF-1α inhibitor, on the progression, migration, and invasion of gastric cancer cells." (PMID 38140111, 2023). "As a result, HIF-1α emerges as a promising target for novel therapeutic strategies that aim to mitigate the progression of gastric cancer." (PMID 38140111, 2023). "We found that a low dose of tipifarnib suppresses the Warburg effect via HIF-1α in breast and gastric cancer cells under normoxia." (PMID 37511305, 2023). "Hypoxia and HIF-1α contribute substantially to tumor progression and chemoresistance in gastric cancer." (PMID 36846589, 2023). "A large-scale meta-analysis in gastric cancer revealed HIF-1α positivity in half of the gastric tumors." (PMID 36846589, 2023). "When they incubated the SGC7901 gastric cancer cells in a hypoxic microenvironment or overexpressed HIF-1α, the efflux of doxorubicin increased significantly, decreasing the intracellular accumulation of the drug." (PMID 36846589, 2023). "HIF-1α expression levels paralleled the severity of gastric disease, with the highest levels among patients with gastric cancer." (PMID 37828903, 2023).